MMP11 (matrix metallopeptidase 11)
Diseases named in the same sentence as MMP11 in open-access papers (continued):
Sharing a sentence is not in itself a finding about the gene and the disease.
breast carcinoma (continued). "Altogether, MMP11 stands as an important metabolic regulator both in physiological energy homeostasis and in the context of breast cancer (BC)." (PMID 32825455, 2020). "There are many MMPs associated with obesity, in particular MMP-11 (also known as stromelysin-3/ST-3) has been shown to be overexpressed by adipocytes as a result of stimulation by invading breast cancer cells." (PMID 33339340, 2020). "In the present work, we have investigated the gene expression of MMP1 and MMP11 in PBMC from breast cancer patients (BC-PBMC), before and after co-culture with breast cancer cell lines or CAF, compared to PBMC from healthy women (C-PBMC)." (PMID 33396463, 2020). "We investigated MMP1 and MMP11 expression in PBMC from breast cancer patients and we analyzed gene expression changes upon their interaction with cancer cells and cancer-associated fibroblasts (CAF)." (PMID 33396463, 2020). "If MMP11 serves as the functional link of miR‐125b in breast cancer cells, re‐expression of MMP11 in miR‐125b overexpressed cells should be able to reverse the effects of miR‐125b." (PMID 32291953, 2020). "The changes in body weight observed in the GOF and LOF breast cancer models recapitulated those already reported in single MMP11-overexpressed and -inactivated mice models." (PMID 32825455, 2020). "Our results show the existence of a subpopulation of breast cancer patients (25.9%) with very high levels of MMP11 gene expression in PBMC." (PMID 33396463, 2020). "Basal gene expression of MMP1 and MMP11 was studied in PBMC from breast cancer patients (BC-PBMC) and healthy women (controls, C-PBMC)." (PMID 33396463, 2020). "We used the UALCAN database to investigate the expression of MMP11 in human breast cancer and adjacent normal tissues." (PMID 32291953, 2020). "The analysis of the MMP11 expression in PBMC suggests the existence of a breast cancer patient subpopulation (25.9% of total patients) showing high levels of MMP11 (2-fold or higher) compared to healthy women." (PMID 33396463, 2020). "miRNA‐125b mimic inhibited proliferation, migration, and invasion of breast cancer cells through targeting MMP11 protein." (PMID 32291953, 2020). "Nevertheless, the present study brings new insights into the role of MMP11 during cancer development in the spontaneous genetic MMTV-PyMT breast cancer mouse model." (PMID 32825455, 2020). "In this study, we demonstrated that miR‐125b can regulate MMP11 expression to fully illustrate the mechanisms involving breast cancer progression." (PMID 32291953, 2020). "Our data indicated that miR‐125b expression was downregulated in breast cancer tissue and mediated cell proliferation, migration and invasion through regulating MMP11, implying that the tumor suppressive role of miR‐125b in breast cancer." (PMID 32291953, 2020). "In breast cancer, matrix metalloproteinase (MMP)-11 is induced in adipocytes by adjacent invading cancer cells." (PMID 33339340, 2020). "In breast cancer cells, MMP11 is overexpressed, with a significant increase in cell migration and invasion." (PMID 32291953, 2020). "Due to the complexity of breast cancer development and individual differences in gene expression, MMP‐11 is likely to participate in multiple steps of breast cancer development and tumor cell invasion and metastasis." (PMID 32291953, 2020). "In order to tackle this issue, we used MMP11 gain-of-function (GOF, MMP11Tg) and loss-of-function (LOF, MMP11KO) mouse models to examine the role of MMP11 on mammary tumor growth and metabolism." (PMID 32825455, 2020). "With both methods we identified up-regulated matrix metalloproteinases (such as MMP11 and MMP13) which are a class of enzyme known to be involved in cancer invasion and metastasis and have been linked to breast cancer outcomes." (PMID 30835723, 2019). "The MMP-11 gene, which is also called stromelysin-3 (ST-3), is located on chromosome 22q11.23 and has been identified in a breast cancer cDNA library." (PMID 30208169, 2018).
breast carcinoma (continued). "A new prognostic model for HR−/HER2+ breast cancer based on the expression of MMP11 and CD2 was developed and the DMFS for patients in the high-risk group according to our model was significantly lower than that for those in the low-risk group." (PMID 28409241, 2017). "Independent prognostic factors for OS in HR−/HER2+ breast cancer included the expression of MMP11 and BTN3A2." (PMID 28409241, 2017). "Recent studies also showed that MMP11 is a downstream target of oncogene or tumor suppressor microRNA, thereby contributes to tumor cell migration, invasion, or angiogenesis in breast cancer cells." (PMID 28409241, 2017). "In HR−/HER2+ breast cancer, MMP11 and three i-genes (BTN3A2, CD2, and TRBC1) were significantly associated with clinical outcomes, whereas no clinical variable was significant." (PMID 28409241, 2017). "The expression of metalloproteinase (MMP)-11/stromelysin-3 in adipocytes is induced by breast cancer cells at the tumour invasive front, indicative of a role in extracellular matrix remodelling during breast cancer development." (PMID 28281525, 2017). "In HR−/HER2+ breast cancer, four genes (three i-genes BTN3A2, CD2, and TRBC1 and the p-gene MMP11) were significantly associated with distant metastasis-free survival (DMFS)." (PMID 28409241, 2017). "In HR−/HER2+ breast cancer, MMP11 (hazard ratio 1.49; 95% CI 1.08–2.04; P = 0.014) and CD2 (hazard ratio 0.66; 95% CI 0.47–0.94; P = 0.022) retained their statistical significance for DMFS in multivariate analysis." (PMID 28409241, 2017). "Higher levels of MMP-11 are expressed by adipocytes at the invasive front of human breast cancers secondary to ECM remodelling in this area." (PMID 29104428, 2017). "Oncogenic transcription factor Gli1 promotes migration and invasion of ER− breast cancer cells through the up-regulation of MMP11 and reduced MMP11 expression mediates the anti-angiogenic and invasion effect of microRNA miR-98 in ER− breast cancer cells." (PMID 28409241, 2017). "MMP-11 overexpression has also been demonstrated to confer a poor prognosis in breast carcinomas and was significantly correlated with the metastasis of hepatocellular carcinoma." (PMID 27028996, 2016). "From our gene microarray data, MMP11 was found to be up-regulated while HPSE2 was down-regulated in breast cancer compared with normal control." (PMID 26084486, 2015). "Further functional and protein-protein interactions studies are needed to clarify a likely correlation between IGFBP5, COL1A1 and MMP11 considering the metastasis process in breast cancer." (PMID 26569312, 2015). "Positive staining (>30%) of MMP-11 expression was obviously associated with shorter OS and DFS in breast cancer, and the influence was even more significant in patients with node-positive metastasis." (PMID 26270045, 2015). "Instead of MMP1, MMP11 is over-expressed in MCF-7 spheroids and in a variety of human carcinomas, and MMP11 expression directly correlates with improved cell-matrix adhesion, tumour development and poor prognosis of breast cancer patients." (PMID 26513020, 2015). "Temporally increased MMP-11 expression can be considered as an early event, occurring prior to lymph node metastasis during breast cancer progression." (PMID 24564996, 2014). "In plasma samples MMP11 protein was present in 5/13 breast cancer patients and in 1/12 prostate cancer patients." (PMID 24564996, 2014). "We found that expression of ALK4 and MMP11 was much higher in human breast carcinoma specimens than in normal breast tissues." (PMID 23211491, 2012). "In previous reports, we found a group of breast cancer tumors characterized by metalloprotease-11 (MMP-11) expression by intratumoral mononuclear inflammatory cells (MICs), which was associated with distant metastasis development." (PMID 23145063, 2012). "We analyzed MMP-11 expression by MICs in breast carcinomas samples, to distinguish the two principal groups of tumors." (PMID 23145063, 2012).
breast carcinoma (continued). "Stromelysin-3 (ST-3, MMP-11) was originally identified as a breast cancer associated gene, which is over-expressed in more than 90% of invasive breast carcinomas." (PMID 17233884, 2007). "The anti-MMP-11 antibody recognised a band of approximately 47 kDa corresponding to the expected size in both, breast carcinomas (lanes 1 and 2), and placenta (lane 3)." (PMID 17848954, 2007). "It has also been associated with malignant progression and invasive potential in breast cancer, and together with MMP11 in colorectal and oesophageal cancer." (PMID 16626496, 2006). "The induction of specific MMPs such as MT1-MMP and MMP-11 have been shown to correlate with tumour invasiveness and resultant metastasis in several human cancers, including breast carcinoma." (PMID 15272933, 2004). "In the same way, in breast cancer, pathway analysis emphasized the role of extracellular matrix disassembly, hormone metabolism, and angiogenesis, where the major players were genes such as MMP11 (facilitating metastasis) and EGR1 (tumor suppressor)." (PMID 40565055, 2025). "To assess if MMP-11 expression, detected through conventional IHC, could aid the management of early breast cancer patients, we examined its expression in a cohort of 228 women, with a median age of 60 years." (PMID 38438841, 2024). "Myofibroblasts are important sources of MMPs in breast cancer, and tumour progression and adverse reactions are associated with strong expression of MMP-1, MMP-7, and MMP-9, as well as fibroblast-specific production of MMP-9, MMP-11, and MMP-1431." (PMID 38956273, 2024). "Specifically: 1) NEK2 is a constituent of the 11-gene Breast Cancer Index signature used to estimate recurrence; and 2) MMP11 is a constituent biomarker of the 50-gene Prosigna, and 21-gene OncotypeDX signature panels, which are both used in estimating likelihood of recurrence." (PMID 37287543, 2023). "Numerous studies have examined an association between MMP-2, MMP-9, and MMP-11 expression and clinicopathological characteristics of breast cancer (BC); however, no research has been done on the MMP expression levels in BC cases from Ethiopia." (PMID 37798646, 2023). "In addition, the relevance of the miR125b-5p/MMP11 interaction in the context of breast cancer biology is yet to be explored." (PMID 37445827, 2023). "Overexpression of circ-MMP11 could induce resistance against lapatinib in breast cancer through acting as a decoy of miR-153-3p and regulating the level of ANLN." (PMID 38186573, 2023). "There is abundant literature assessing the link between MMP11 and breast cancer." (PMID 37391533, 2023). "In breast cancer, MMP11 expression was considered as a biomarker for prognosis, and correlated with a high CD68/(CD3 + CD20) ratio in CD68+ macrophages, which caused the polarisation of macrophages in the tumour centre, resulting in a higher metastatic phenotype." (PMID 36683048, 2023). "Likewise, CAAs cocultured with breast cancer cells have been shown to increase their expression of MMP-11 as well as proinflammatory cytokines (IL-6 and IL-1β) and thereby promote tumor cell invasion and metastasis." (PMID 36670988, 2023). "Circ-MMP11 is upregulated in lapatinib-resistant breast cancer." (PMID 38186573, 2023). "Interestingly, MMP11 has been shown to be expressed both by CAFs, adipocytes as well as mononuclear inflammatory cells in breast cancer and to be significantly correlated with immune cell infiltration." (PMID 37391533, 2023). "Additionally, MMP11-expressing macrophages play a role in promoting tumor through via the upregulation of PD-L1 expression and inducing immunosuppression in breast cancer cells." (PMID 36591235, 2022). "MMP11 expression by cancer‐associated fibroblasts (CAFs) and intratumoral mononuclear inflammatory cells (MICs) was associated with relapse‐free survival (RFS) and overall survival (OS) in breast cancer." (PMID 34981672, 2022).
breast carcinoma (continued). "This study revealed that MMP-11 in the TME has different functions in breast cancer progression." (PMID 36741729, 2022). "miR‐125b is known to regulate MMP11 expression in breast cancer." (PMID 34981672, 2022). "MMP-11 has a dual role in breast cancer, depending on the stage of cancer." (PMID 36741729, 2022). "However, the mechanistic roles of MMP-11 in the regulation of the immune response in the TME are unclear, and further studies are required to elucidate the immune response-related role of MMP-11 in breast cancer progression." (PMID 36741729, 2022). "Other studies have shown the tumor-promoting effects of tumoral MMP-11 in breast cancer." (PMID 36741729, 2022). "One of the MMP members, MMP-11, called stromelysin-3, was first identified in breast cancer tissue." (PMID 34038440, 2021). "In addition, the functional analysis suggested that the downregulation of ANLN partly reversed the suppressive role of exo-circ-MMP11 on cell growth and metastasis in breast cancer cells." (PMID 34295807, 2021). "In summary, these results discovered that circ-MMP11 could be transferred by exosomes, and circ-MMP11 could elevate lapatinib resistance by regulating the miR-153-3p/ANLN axis in breast cancer cells." (PMID 34295807, 2021). "In a word, circ-MMP11 knockdown improved lapatinib sensitivity of breast cancer in vivo." (PMID 34295807, 2021). "Also, we performed in vitro drug screening tests in breast cancer cell lines according to MMP-11 expression to identify suitable target therapy." (PMID 34038440, 2021). "Moreover, our data suggested that exosomal circ-MMP11 level was increased in LR breast cancer tissues." (PMID 34295807, 2021). "In this work, circ-MMP11 was first identified to display the high expression in LR breast cancer tissues and cells, implying that circ-MMP11 might participate in the lapatinib resistance in breast cancer." (PMID 34295807, 2021). "Furthermore, circ-MMP11 knockdown promoted lapatinib sensitivity by repressing cell viability, colony number, migration, invasion, and boosting apoptosis in LR breast cancer cells." (PMID 34295807, 2021). "We considered that MMP-11 could play an important role in breast cancer progression and metastasis and predicting clinical outcomes." (PMID 34038440, 2021). "Furthermore, to identify the functional role of circ-MMP11 on lapatinib resistance in vivo, mice xenograft models of breast cancer were established." (PMID 34295807, 2021). "We investigated the clinicopathologic parameters, specific gene sets, tumor antigenicity, and immunologic relevance according to MMP-11 expression in 226 and 776 breast cancer patients from the Hanyang University Guri Hospital (HUGH) cohort and The Cancer Genome Atlas (TCGA) data, respectively." (PMID 34038440, 2021). "Meanwhile, circ-MMP11 was also predominantly located in the cytoplasm of MDA-MB-231/LR and MCF-7/LR cells, manifesting the underlying post-transcriptional regulatory mechanism of circ-MMP11 in LR breast cancer cells." (PMID 34295807, 2021). "Similarly, suppression of LINC01561 can inhibit cancer cell proliferation and facilitate apoptosis in breast cancer via increasing expression of miR-145-5p as well as reducing expression of MMP11." (PMID 33836753, 2021). "Besides, our data also suggested that exo-circ-MMP11-secreted by LR breast cancer cells accelerated lapatinib resistance, proliferation, migration, invasion of breast cancer cells by regulating the miR-153-3p/ANLN axis." (PMID 34295807, 2021). "Given that circ-MMP11 could be transferred by exosomes in breast cancer, and the effects of GW4869 on miR-153-3p and ANLN in this assay." (PMID 34295807, 2021). "In this paper, our data verified that circ-MMP11 knockdown could enhance the lapatinib sensitivity, hinder cell viability, colony number, migration, invasion, and induce apoptosis in LR breast cancer cells in vitro." (PMID 34295807, 2021).
breast carcinoma (continued). "Besides, we detected that the authentic effect of circ-MMP11 on miR-153-3p level in LR breast cancer cells." (PMID 34295807, 2021). "To evaluate the relationship between the high expression of MMP11 and the immune response in breast cancer patients, we focused on evaluating the high expression of MMP-11 associated immune gene sets and genes, the different types of involved immune cells and network-based pathway." (PMID 34038440, 2021). "Here, miR-153-3p as a target of circ-MMP11 was verified in LR breast cancer cells." (PMID 34295807, 2021). "Protein degradation by MMP-11 in tumor cells may progressively suppress cancer surveillance activities with blocking immune response in breast cancer." (PMID 34038440, 2021). "Also, gene expression of MMP1 and MMP11 increases in PBMC after co-culture with breast cancer cell lines, NF or CAF." (PMID 33396463, 2020). "This study found that MMP11 was significantly upregulated in breast cancer tissues." (PMID 32291953, 2020). "MMP11 has also been reported as a novel prognostic factor in breast cancer." (PMID 33194682, 2020). "In addition, MMP11 is expressed by breast cancer intratumoral mononuclear inflammatory cells and this expression is the most potent and independent factor to predict relapse-free survival and overall survival." (PMID 32825455, 2020). "However, IL1A, IL6, IL10, and NFĸB gene expression in CAF was increased, whereas MMP11 was decreased after co-culture with PBMC from breast cancer patients." (PMID 33396463, 2020). "In addition, the expression of MMP11 between breast cancer tissue with normal breast tissue were initially analyzed by using UALCAN database." (PMID 32291953, 2020). "Some studies have found that MMP‐11 may be involved in the invasion and metastasis of breast cancer, but the functional role of MMP‐11 is still unclear." (PMID 32291953, 2020). "In our study, we investigated the roles of MMP11 in breast cancer cells." (PMID 32291953, 2020). "MMP11 was first discovered in breast cancer and has antiapoptotic functions." (PMID 32291953, 2020). "In addition, we found that miRNA‐125b spoiled MMP11 induced breast cancer cell proliferation and migration promotion effect." (PMID 32291953, 2020). "MMP-11 and MMP13 expression were also promising markers linked to the poor outcome of breast cancer which may be a novel target for the treatment of breast cancer." (PMID 31398937, 2019). "During breast cancer progression MMP11 expression is significantly increased in IBC compared to DCIS, supporting our data that it may be a key player driving the DCIS-to-IBC transition." (PMID 30236106, 2018). "The roles of MMP11 in tumor progression have been reported in breast cancer." (PMID 28409241, 2017). "Moreover, breast cancer dataset downloaded from The Cancer Genome Atlas showed that patients with higher level of MMP-11 or PDGF-C expression had shorter survival time than those with lower level of these proteins." (PMID 26456994, 2015). "So we anticipate that IGFBP5 could be a possible modifier on metastatic capacity of breast cancer through regulating COL1A1 or MMP11." (PMID 26569312, 2015). "In the present study, we hypothesized that IL-33 was associated with invasion and angiogenesis of breast cancer and investigated whether serum IL-33 or sST2 was correlated with VEGF, PDGF-C, or MMP-11." (PMID 26456994, 2015). "A recent study also showed that MMP-11 could be as a promising biomarker for breast cancer and a suitable target for cancer immunotherapy strategies." (PMID 25423087, 2014). "Furthermore, the prognostic significance of MMP11 expression was further confirmed for breast cancer and shown for prostate cancer." (PMID 24564996, 2014). "Finally, ALK4- and MMP11-specific siRNAs inhibited breast cancer cell proliferation, survival, and angiogenesis." (PMID 23211491, 2012). "Additionally, other MMPs, notably MMP11, have been shown to be correlated with breast cancer-induced adipocyte's activated state." (PMID 22469146, 2012).